MEN1 (menin 1)
Diseases named in the same sentence as MEN1 in open-access papers (continued):
Sharing a sentence is not in itself a finding about the gene and the disease.
multiple endocrine neoplasia type 1 (continued). "All children with genetically confirmed MEN1 syndrome developed various MEN1 components during next 2-13 years with hyperparathyroidism and hyperprolactinemia being the most common findings (n=5 and 3 resp)." (PMID 37152923, 2023). "Menin, the product of the MEN1 (multiple endocrine neoplasia type 1) tumor-suppressor gene was shown to physically interact with the PPARα protein to control the expression of genes involved in fatty-acid oxidation." (PMID 35954274, 2022). "This patient was also screened for the presence of MEN-1 (multiple endocrine neoplasia type 1) or AIP (aryl hydrocarbon receptor-interacting protein) mutations." (PMID 36157469, 2022). "Rarely, PBMAH can occur as part of genetic tumor predisposition syndromes such as familial adenomatous polyposis (APC), multiple endocrine neoplasia type 1 (MEN1) and hereditary leiomyomatosis (FH)." (PMID 36105398, 2022). "Multiple endocrine neoplasia type 1 (MEN1), an autosomal-dominantly inherited tumor syndrome, is classically defined by tumors arising from the “3 Ps”: Parathyroids, Pituitary, and the endocrine Pancreas." (PMID 36325452, 2022). "Two patients were carriers of MEN1 (Multiple Endocrine Neoplasia Type 1) and one patient of VHL (Von Hippel-Lindau disease)." (PMID 36358607, 2022). "Multiple endocrine neoplasia type 1 (MEN1) is an autosomal dominant hereditary syndrome with high penetrance; the mutated tumor suppressor gene MEN1 (chromosome 11q13) causes tumors to form in the endocrine glands." (PMID 36382757, 2022). "Moreover, as the MEN1 gene is frequently deleted and mutated also on the somatic level in sporadic parathyroid adenomas, additional factors are needed to bring into consideration before suspecting MEN1 syndrome–related PHPT from expressional analyses in the pathology laboratory." (PMID 33269427, 2021). "Multiple endocrine neoplasia type 1 (MEN1) is a rare tumor syndrome with an autosomal dominant inheritance, and genetic testing for MEN1 gene is important for both affected individuals and their relatives." (PMID 34160414, 2021). "We anticipate that this isogenic system will be broadly useful to comprehensively study MEN1 gene function across different contexts, including in vitro modeling of MEN1 syndrome." (PMID 34769484, 2021). "Multiple Endocrine Neoplasia type 1 (MEN1) is a familial syndrome that results from the disruption of a tumor suppressor protein called MENIN." (PMID 34889280, 2021). "Mouse strains with defective Men1 possess remarkable phenotypic and histological overlap with the human MEN1 syndrome." (PMID 31160716, 2020). "MEG3, which is downregulated in multiple cancer cell lines, is epigenetically activated upon the methylation of histone H3 at lysine 4 (H3K4me3) by MEN1 (multiple endocrine neoplasia type 1), a component of the MLL complex that functions as a tumor suppressor." (PMID 33291485, 2020). "Genetic syndromes such as multiple endocrine neoplasia type 1 (MEN1), Von Hippel-Lindau (VHL) and neurofibromatosis type 1 (NF1) have been associated with NENs, but they only account for about 10% of observed cases." (PMID 32245472, 2020). "Multiple endocrine neoplasia type 1 (MEN1) or Wermer's syndrome is a genetic disease characterized by involvement of multiple endocrine glands, primarily involving parathyroid, pancreas, and pituitary." (PMID 33489491, 2020). "Multiple endocrine neoplasia type 1 (MEN1) is a genetic syndrome in which patients develop neuroendocrine tumors (NETs), including pancreatic neuroendocrine tumors (PanNETs)." (PMID 31160716, 2020). "The influence of genetic background on the phenotypes of embryonic lethality and neural defects has also previously been reported in homozygous Men1-/- mouse embryos, implicating a role for genetic modifiers in MEN1 syndrome." (PMID 32348957, 2020).
multiple endocrine neoplasia type 1 (continued). "Multiple endocrine neoplasia type 1 (MEN1) is a rare, autosomal dominantly inherited tumor syndrome caused by germline mutations of the tumor suppressor MEN1 gene, with an estimated prevalence of 1–10/100,000 individuals." (PMID 31044390, 2019). "Clinical suspicion of MEN1 syndrome emerged at significantly earlier age in MEN1-positive compared to MEN1-negative probands." (PMID 31044390, 2019). "Multiple endocrine neoplasia type 1 (MEN1) is a rare autosomal dominant inherited condition affecting multiple endocrine organs, resulting in significant morbidity and decreased life expectancy." (PMID 31727021, 2019). "Risk factors for PNETs include smoking, a high body mass index, and a positive family history which accounts for a variable percentage of patients with inherited syndromes, such as multiple endocrine neoplasia type 1 (known as MEN1)." (PMID 31296241, 2019). "Apart from the 27 genetically confirmed MEN1 index cases, 77 unrelated index patients with signs and symptoms resembling MEN1 syndrome were referred to our laboratory." (PMID 31044390, 2019). "Preimplantation genetic diagnosis was carried out for embryonic analysis in apatient with multiple endocrine neoplasia type 1 (MEN1)." (PMID 29266898, 2018). "More than 1000 families presenting with MEN1 syndrome have been described since the cloning of the MEN1 gene in 1997." (PMID 29416715, 2018). "Heterozygous Men1 mutant mice mimic the human MEN1 syndrome and develop multiple endocrine tumors, mainly in the pancreas, parathyroid, and less frequently in the adrenal gland." (PMID 29335487, 2018). "PCas have been occasionally reported also in patients affected with multiple endocrine neoplasia type 1 syndrome (OMIM#131100), harboring inactivating mutations of the MEN1 gene." (PMID 28157158, 2017). "Multiple endocrine neoplasia type 1 (MEN1) was excluded from her family history, and serum levels of both intact parathyroid hormone (iPTH) and calcium were within normal ranges." (PMID 29181825, 2017). "Multiple endocrine neoplasia type 1 (MEN1, OMIM #131100) is an autosomal dominant inherited disease characterized by the occurrence of several endocrine tumors." (PMID 27846313, 2016). "Three (2.4 %) patients had confirmed von Hippel- Lindau syndrome, and one patient had multiple endocrine neoplasia type 1 (MEN1)." (PMID 26911576, 2016). "MEN1 and RET are associated with multiple endocrine neoplasia type I and multiple endocrine neoplasia type II, respectively." (PMID 26530882, 2015). "Multiple endocrine neoplasia type 1 (MEN-1 syndrome), a hereditary condition associated with tumors of the endocrine (hormone producing) glands, and the tumor suppressor gene MEN1 is frequently mutated in this disease." (PMID 26343727, 2015). "MEN1, which is also referred to as Wermer’s syndrome is characterized by the combined occurrence of tumors of the parathyroid glands, the pancreatic islet cells, and the anterior pituitary." (PMID 23933118, 2014). "Especially, the aspect of chemoprevention in patients with Multiple Endocrine Neoplasia Type 1 (MEN1) cannot be overestimated." (PMID 24213240, 2012). "Diagnosis of multiple endocrine neoplasia type 1 (MEN1) is commonly based on clinical criteria, and confirmed by genetic testing." (PMID 23259638, 2012). "According to the current guidelines an individual affected by two or more primary MEN1-related endocrine tumors should be suspected to have the MEN1 syndrome." (PMID 23259638, 2012). "Genetic testing confirmed suspicions of MEN1 syndrome and showed MEN1 heterozygous Cys241Tyr." (PMID 41541958, 2025). "Furthermore, we confirmed six cases with a hereditary background (Multiple Endocrine Neoplasia type 1, MEN1), showing NENs in multiple organ tissues." (PMID 40281248, 2025).
multiple endocrine neoplasia type 1 (continued). "A few cases were associated with multiple endocrine neoplasia type 1, which is linked to loss of heterozygosity on 11q13 and inactivating mutations of the MEN1 gene, yet data suggest that menin does not play a causative role in the tumorigenesis of TAs." (PMID 41303810, 2025). "Finally, in 2015, a German group reported a case of multiple endocrine neoplasia type 1 (MEN1) in a 47-year-old man carrying both a novel EXT1 mutation and a pathogenic variant in the MEN1 gene." (PMID 41441317, 2025). "The next-generation sequencing panel for multiple endocrine neoplasia type 1 identified a probably pathogenic variant c.442A>C: p.(Thr148Pro) in heterozygosity in the MEN1 gene, without previous description in databases (ClinVar)." (PMID 40136120, 2025). "These preliminary data suggest circulating miR-1301-3p and miR-24-3p as potential non-invasive diagnostic biomarkers for MEN1 syndrome, regardless of different clinical phenotypes and MEN1 mutation types." (PMID 40507887, 2025). "Metastatic PC may occur sporadically (90%) or in association with inherited cancer syndromes (10%), including hyperparathyroidism-jaw tumor syndrome, multiple endocrine neoplasia type 1 (MEN1), or multiple endocrine neoplasia type 2A (MEN2A)." (PMID 39011405, 2024). "Furthermore, PC can develop in multiple endocrine neoplasia type 1 due to germline and somatic MEN1 gene inactivation." (PMID 39056047, 2024). "The vast majority of PanNETs are sporadic, but approximately 17% are associated with an inherited syndrome, the most common being Multiple Endocrine Neoplasia type 1 (MEN1), von Hippel–Lindau (VHL) syndromes, Neurofibromatosis type 1 (NF1), and Tuberous Sclerosis Complex (TSC)." (PMID 38893191, 2024). "MEN1 mutations seem to be a discriminating factor associated with the classic phenotype of MEN1 syndrome, whereas most of the MEN1 mutation-negative patients have a different phenotype and clinical course of the disease, representing the so-called phenocopies." (PMID 37484956, 2023). "Unfortunately, in the majority of sporadic cases the absence of MEN1 syndrome, i.e. a germline MEN1 mutation, was not excluded." (PMID 37199453, 2023). "Only up to 5% of them are hereditary and can be caused, e.g. by MEN1 or aryl hydrocarbon receptor-interacting protein (AIP) gene mutations, and present as a part of multiple endocrine neoplasia type 1 (MEN1) or familial isolated pituitary adenoma (FIPA) syndromes." (PMID 36843582, 2023). "The autosomal dominant multiple endocrine neoplasia type 1 (MEN1) syndrome in which tumors arise in select endocrine tissues, including the parathyroid glands, and in non‐endocrine tissues is caused by loss‐of‐function mutations in the tumor suppressor gene, MEN1." (PMID 35509630, 2022). "MEN1 syndrome is caused by MEN1 tumor suppressor gene germline inactivation mutation and normal allele somatic cell loss." (PMID 36248960, 2022). "Panel testing is now used in clinical practice to investigate familial hypercalcemia or syndromic/familial MEN1 syndrome at initial presentation, or in MEN1-mutation-negative patients." (PMID 35323929, 2022). "This is not a setback in the study of Men1 loss in mice as patients of MEN1 syndrome also develop pituitary tumors in addition to pNETs." (PMID 34680266, 2021). "In an attempt to recognize early molecular alterations, we used adrenals from young multiple endocrine neoplasia type 1 conventional knock-out mice (Men1+/−) closely mimicking the human MEN1 trait (i.e. transformation of pituitary, parathyroid, endocrine pancreatic, and adrenocortical cells)." (PMID 34285285, 2021). "To date, few cases of primary ovarian NETs in women with MEN1 syndrome have been described in association with clinical manifestations of MEN1, but without genetic testing." (PMID 33312161, 2020). "Given the association between insulinoma and multiple endocrine neoplasia type 1 (MEN1), he underwent genetic testing, but no known mutations were identified in MEN1." (PMID 32605595, 2020).
multiple endocrine neoplasia type 1 (continued). "The suspicion of MEN1 syndrome emerged at significantly earlier age in MEN1 mutation carriers compared to non-carriers (31.4 ± 12.6 vs. 40.2 ± 17.3 years, p = 0.019)." (PMID 31044390, 2019). "We also detected an established pathogenic variant for multiple endocrine neoplasia type 1 (MEN-1) syndrome, in MEN1 (ENST00000337652:c.778G > A, p.Glu260Lys, rs104894268) in a non-index patient, diagnosed with BC and primary parathyroid hyperplasia at 50 years." (PMID 31681433, 2019). "High-impact MEN1 mutation carriers were more likely to develop GEP-NETs than patients with low-impact mutations, resulting in a geno-phenotype correlation, which is of importance regarding the genetic counseling and the prognosis of MEN1 syndrome." (PMID 31044390, 2019). "Studies of hereditary and syndromic forms of PC, which include the hyperparathyroidism‐jaw tumor syndrome (HPT‐JT), multiple endocrine neoplasia types 1 and 2 (MEN1 and MEN2), and familial isolated primary hyperparathyroidism (FIHP), have revealed some genetic mechanisms underlying PC." (PMID 28881068, 2017). "Northern blotting revealed that FKBP2 is expressed in tissues that are predisposed to hyperplasia in multiple endocrine neoplasia type 1 (MEN1) patients; however, mutation analysis of MEN1 kindreds and sporadic tumors excluded FKBP2 as a candidate gene for MEN1." (PMID 28152021, 2017). "These NETs may occur as an isolated endocrinopathy, which may be inherited as occurring in familial isolated pituitary adenomas, or they may occur as part of a complex hereditary syndrome, such as multiple endocrine neoplasia (MEN) type 1 (MEN1)." (PMID 26990064, 2016). "Germline inactivating mutations of the MEN1 gene cause a complex genetic syndrome named multiple endocrine neoplasia type 1 (MEN1) characterized by endocrine and non-endocrine tumors." (PMID 27471492, 2016). "Recently, research concerning other genes has been performed trying to explain the MEN1 clinical phenotype in cases of a mutation-negative MEN1 syndrome." (PMID 27842554, 2016). "Menin, the tumour suppressor product of the MEN1 gene that is mutated in the human tumour predisposition syndrome multiple endocrine neoplasia type 1 (MEN1), is a 610 amino acid protein with no homology to any known proteins." (PMID 22708734, 2012). "The MEN1 tumor suppressor gene was identified in 1997 as the gene responsible for the autosomal dominant syndrome characterized by tumors of endocrine pancreas, the anterior pituitary and parathyroid glands, the MEN1 syndrome." (PMID 22567348, 2011). "The patient underwent genetic testing for Cowden syndrome (PTEN gene), Carney complex (PRKAR1A gene), and multiple endocrine neoplasia syndrome type 1 (MEN1 gene); no deleterious mutations were identified." (PMID 17411461, 2007). "Multiple endocrine neoplasia type 1 (MEN-1; OMIM 131100) is a rare, autosomal dominant syndrome caused by heterozygous inactivating mutations in the MEN1 tumor suppressor gene (11q13; OMIM 613733)." (PMID 41323978, 2025). "MEN1 is a tumor suppressor gene associated with multiple endocrine neoplasia type 1 and many sporadic endocrine tumors, such as parathyroid tumors, pancreatic insulinomas, and pituitary adenomas, suggesting somatic MEN1 mutations play a role in nonhereditary endocrine tumors." (PMID 39056047, 2024). "However, considering the clinical parallels with MEN1 syndrome, it is posited that screening protocols tailored to MEN1-related conditions may offer a foundational template for guidance." (PMID 39201946, 2024). "The most frequent familial condition associated with rf-pNENs is multiple endocrine neoplasia type 1 (MEN1), with glucagonomas occurring in 5% and VIPomas in 3% of MEN1 patients." (PMID 39122816, 2024).
multiple endocrine neoplasia type 1 (continued). "Similarly, The Endocrine Society endorses genetic counseling and testing to patients with multiple endocrine neoplasia type 1 (MEN1) and also to their first-degree relatives to check for inherited endocrinopathies which are rare and are linked with substantial morbidity and mortality." (PMID 38638122, 2024). "A founder effect in Newfoundland and Labrador has been identified in the prevalence of several malignancy-associated Mendelian disorders such as MEN1 (multiple endocrine neoplasia type 1) and HNPCC (hereditary non-polyposis colorectal cancer, also known as Lynch Syndrome)." (PMID 37999115, 2023). "PC was very rarely associated with a familial history (0.6% of cases in the contest of HPT-JT syndrome) and with a Multiple Endocrine Neoplasia type 1 (MEN1) syndrome (0.3% of cases in MEN1)." (PMID 37834940, 2023). "Among familial endocrine tumor syndromes, multiple endocrine neoplasia type 1 (MEN1) is distinctive because CS in MEN1 can result from both ACTH-dependent and ACTH-independent causes." (PMID 37409236, 2023). "Multiple endocrine neoplasia type 1 (MEN1) is an inherited tumour endocrine syndrome, with the parathyroid glands, anterior pituitary gland and pancreas as the main sites of MEN1-related neuroendocrine tumours (NETs)." (PMID 36694894, 2022). "Therefore, in an acromegaly/gigantism patient with features of the MEN1 syndrome but without MEN1 mutations, screening for CDKN1B mutations is indicated." (PMID 28161730, 2017). "Up to 10% of patients with MEN1 syndrome may not harbor mutations in the coding regions of the MEN1 gene, but in the gene promoter or untranslated regions, challenging the genetic diagnosis." (PMID 27418145, 2016). "In about 10% of individuals bearing characteristics of MEN1 syndrome, no MEN1 causative variant is identified, either due to the presence of structural variants, or due to the presence of variants in a gene’s promoter and untranslated regions, phenomena that might not be routinely identified." (PMID 35407574, 2022). "MEN1 (MIM# 131100), also known as Wermer's syndrome, is characterized by the occurrence of parathyroid, pancreatic islet, and anterior pituitary tumors." (PMID 28881068, 2017). "In most cases, the patient has multiple endocrine neoplasia type I (MEN-1) and should be investigated with serum sequencing for MEN1 gene." (PMID 29257854, 2017). "Therefore, potential cases of rare isolated PHPT caused by MEN1 mutation or late-onset MEN1 syndrome could not be fully excluded." (PMID 27846313, 2016). "It is also important to note that approximately 5–10% of clinically diagnosed multiple endocrine neoplasia type 1 (MEN1) patients have negative genetic test results and that MEN1 has been proposed to predispose individuals to the development of breast cancer." (PMID 38772934, 2024). "In this retrospective study, the presence of a condition of multiple endocrine neoplasia type 1 (MEN1) did not significantly modulate any of the outcomes evaluated, namely, radiological response, OS, and PFS." (PMID 38137624, 2023). "Local pathology archives were searched for parathyroid tumors from patients with MEN1 syndrome and without MEN1, including sporadic, patients with multiple endocrine neoplasia type 2A and hyperparathyroidism-jaw parathyroid tumors." (PMID 37199453, 2023). "Forty-eight of the forty-nine (98%) non-metastatic tumours expressed GLP-1R, while one non-metastatic, multiple endocrine neoplasia type 1 (MEN1)-related tumour and all three of the metastatic tumours lacked GLP-1R expression." (PMID 37894845, 2023). "Despite the absence of suspicious family history and minimal clinical presentations, four of out the five MEN1 parental carriers and two additional relatives were found to have components of MEN1 syndrome, but none compatible with insulinoma." (PMID 37152923, 2023).